INS (insulin)
Diseases named in the same sentence as INS in open-access papers (continued):
Sharing a sentence is not in itself a finding about the gene and the disease.
Insulin resistance (continued). "Additionally, diabetic patients treated with a collection of probiotics, including B. bifidum (2 × 109 cfu/mL) daily for 12 weeks, significantly decreased insulin resistance, fasting blood glucose, and increased insulin sensitivity and HDL cholesterol level." (PMID 37175825, 2023). "However, in the setting of insulin resistance, the vasodilatory effect of insulin is lost, while the renal effect on sodium reabsorption is preserved." (PMID 38046756, 2023). "The releasing of high levels of NEFAs will affect the peripheral insulin uptake, leading to the hypothesis of insulin resistance and a decreased SOD level." (PMID 37432193, 2023). "Children of South Asian and black African Caribbean origins had markedly lower total 25(OH)D and 25(OH)D3 concentrations; adjustment for these differences reduced the higher levels of fasting insulin and insulin resistance among South Asian and black African Caribbean children by at least 40%." (PMID 38123968, 2023). "Weight gain is usually associated with increased insulin resistance, which often leads to higher circulating insulin levels, not lower." (PMID 38139760, 2023). "In insulin-resistant obese individuals, more than 80% of glucose disposal occurs independently of the dynamic insulin response, which is likely to be increased in individuals with T2D with severe insulin resistance and relative insulinopenia." (PMID 38020201, 2023). "This last disorder disrupts the insulin signaling cascades and initiates a state of insulin resistance which may leads to type 2 diabetes." (PMID 36829899, 2023). "In the present study, bariatric surgery significantly improved insulin resistance and microcirculation disorders in patients with obesity; meanwhile, baseline insulin level was negatively correlated with the changes of retinal vessel densities 6 months after surgery." (PMID 36872300, 2023). "In a study of mice fed a medium-fat or high-fat diet, it was observed that low insulin levels significantly increased lifespan, high insulin levels contributed to age-dependent insulin resistance, and decreased basal insulin levels could extend lifespan." (PMID 37408986, 2023). "Furthermore, inflammatory and ER stress signaling pathways lead to insulin resistance progression through the inhibition of insulin signaling and the activation of the enzymes responsible for gluconeogenesis." (PMID 37998747, 2023). "We are working on follow-up studies to identify whether CNS insulin resistance in select brain regions impacts regional or global insulin BBB transport." (PMID 37076875, 2023). "Insulin resistance is a state of attenuated biological response of tissues to insulin action." (PMID 36979649, 2023). "Moreover, decreased activation of the PI3K/AKT pathway can also reduce insulin secretion and impair β cell function, further aggravating insulin resistance in multiple tissues." (PMID 38028559, 2023). "Third, this study may not have sufficient power to adequately analyze secondary endpoints such as FPI, C-peptide, insulin sensitivity, insulin resistance, and the incidence of T2D." (PMID 38111052, 2023). "Although there is distinct evidence that insulin resistance occurs in syndromes featuring dwarfism, the potential link between insulin sensitivity and cell autonomous defects in DNA replication and/or DNA damage responses remains unclear." (PMID 36627765, 2023). "The anti-lipolytic function of insulin is impaired in insulin resistance, which may facilitate hepatic TG synthesis." (PMID 37895151, 2023). "However, the NPG showed a significantly greater unadjusted reduction in insulin level (d = −0.82, p = 0.01) and insulin resistance (d = −0.78, p = 0.02); these reductions had large and medium effect sizes in favor of the NPG, respectively." (PMID 38068805, 2023).
Insulin resistance (continued). "However, the molecular connection between insulin resistance and estrogen deficiency has been attributed to GLUT4, the primary glucose transporter responsible for insulin-stimulated glucose uptake in muscle and adipocytes." (PMID 38025203, 2023). "Thus, in vitro studies of vindoline in insulin resistant skeleton muscle and dysfunctional adipocytes confirmed that vindoline treatment significantly mitigated insulin resistance in myotubes and improved functional status of adipocytes." (PMID 37447192, 2023). "For hibernators, however, there is considerable literature on glucose, insulin, and reversible insulin resistance, in large part, to probe how hibernators can naturally withstand seasonal obesity and starvation, conditions that can be detrimental in non-hibernators, like humans." (PMID 37745231, 2023). "Mechanistically, our associations support the suggested role of dietary nitrites observed in experimental studies, through N-nitroso compounds, in the development of insulin resistance via a disruption of insulin and IGF signaling pathways, and a dysfunction of pancreatic β cells." (PMID 36649248, 2023). "HUA is causally related with insulin resistance, and thus might also be improved by DASH diet, which has the potential to enhance insulin sensitivity." (PMID 36991418, 2023). "It has been demonstrated that moderate alcohol consumption may have a protective role against insulin resistance, potentially improving insulin sensitivity and glycated haemoglobin values." (PMID 36983739, 2023). "Further, in our study, the finding that most MVPA in the afternoon and evening was associated with reduced insulin resistance mainly resulted from lower fasting insulin rather than differences in fasting glucose concentrations." (PMID 36316401, 2023). "Free amino acid levels generated by overexpression of ACY1 play a role in insulin secretion and glucose homeostasis and could eventually lead to T2D with impaired ß-cell function and insulin resistance." (PMID 36777185, 2023). "However, this increased insulin secretion, combined with high levels of circulating lipids and the consequent increase in visceral adiposity, often results in the development of insulin resistance in maternal cells." (PMID 38201896, 2023). "Insulin resistance is a condition in which the activity of the hormone is insufficient to satisfy the metabolic requirements of peripheral tissue, despite an increase in insulin levels." (PMID 36751233, 2023). "Crocin can improve insulin resistance and increase insulin sensitivity." (PMID 36624538, 2023). "With the increase in ferritin levels, the blood glucose and insulin levels gradually increase, further aggravating insulin resistance, which is a potential mediating factor in the relationship between serum ferritin and NAFLD, and obesity, which is one of the risk factors for NAFLD." (PMID 37674440, 2023). "Most epidemiologic and clinical studies consistently show that saturated fat intake is tightly associated with the pathogenesis of insulin resistance and T2DM, whereas polyunsaturated fat intake is significantly associated with improved insulin sensitivity and glucose tolerance." (PMID 37960324, 2023). "Further study indicated that FC could regulate the insulin signal pathway to improve insulin resistance." (PMID 37710214, 2023). "During pregnancy, it is likely to contribute (along with other gestational hormones) to progressive gestational insulin resistance and act, alongside hPL, as a key stimulus for the parallel compensatory process of maternal pancreatic beta-cell adaptation and increased insulin secretion." (PMID 36769162, 2023). "We hypothesized that the adipocytes of our patient are intrinsically insulin-resistant, leading to steatosis of the lean organs (including islet beta-cells), hepatic and muscle insulin resistance, and beta-cell apoptosis." (PMID 38260129, 2023).
Insulin resistance (continued). "However, when OADs fail to counteract serious β-cell dysfunction and/or insulin resistance, the add-on therapy with insulin or the replacement of OADs with insulin is necessary." (PMID 36902770, 2023). "The same bad habit of overeating is undoubtedly dangerous, but the development of insulin resistance gives the patient a chance to start controlling their overconsumption of food, ultimately enabling them to live longer, while the insulin sensitivity in MHO patients leads to a quick, sudden death." (PMID 38003366, 2023). "In vitro, increased CCN2 mRNA expression or protein production was shown to result from the exposure of cultured Day 4 primary rat HSC to glucose or insulin to mimic, respectively, the hyperglycemia or insulin resistance that are frequently seen in NASH patients." (PMID 37629004, 2023). "Previously, when the isotope tracer approach was applied, it pinpointed that NAFLD patients produced elevated glucose concentration (hepatic insulin resistance) and lower glucose uptake (peripheral insulin resistance) in spite of increased insulin levels in comparison to the healthy subjects." (PMID 37854184, 2023). "For example, chronic insulin resistance could interfere with the normal regulation of circadian rhythms because insulin regulates glucose absorption and metabolism in the body, which is critical for maintaining the circadian rhythm." (PMID 37905958, 2023). "These miRNAs may not only be involved in the regulation of insulin signaling pathways and insulin resistance in common carp but also be the markers for liver insulin resistance in MS therapy for the remission of insulin resistance." (PMID 37091861, 2023). "Therefore, PHE administration can result in insulin resistance by induction of a post-binding defect in insulin action." (PMID 37334286, 2023). "In addition to the liver, adipose tissue, and muscle, accumulated evidence indicates that endothelium plays a crucial role as an insulin target, participating in the development of metabolic insulin resistance provoked by the Western diet." (PMID 38107110, 2023). "The molecular mechanisms by which insulin regulates muscle metabolism and the underlying defects that cause insulin resistance have not been fully elucidated." (PMID 38136941, 2023). "Furthermore, changes in the circulating miRNA-192 and miRNA-375, were positively associated with plasma glucose, insulin, and HOMA-IR, indicating that an increase in these miRNA levels mirror an increase in insulin resistance." (PMID 36839236, 2023). "UCG-002 has been negatively associated with obesity and insulin resistance, suggesting that UCG-002 may be involved in mechanisms that improve insulin sensitivity." (PMID 37711620, 2023). "With reference to previous reports on adiponectin, we hypothesized that AdipoRaMab counteracts insulin resistance by improving insulin sensitivity and investigated the plasma glucose–lowering effect of AdipoRaMab in an insulin tolerance test (ITT)." (PMID 37948516, 2023). "In skeletal muscles, insulin resistance is mainly characterized by a decreased Glc uptake caused by the inefficient mobilization of Glc transporters (GLUT-4), which are normally increased upon insulin induction." (PMID 38067472, 2023). "Our findings showed that the higher DDRRs is associated with a lower level of lipid profiles (serum triglycerides (TGs)), insulin profiles (insulin level and homeostasis model assessment-insulin resistance (HOMA_IR)), liver enzymes (aspartate aminotransferase (AST) and alanine transaminase (ALT))." (PMID 37208390, 2023).
Insulin resistance (continued). "Insulin resistance refers to the diminished physiological response of specific organs or tissues in the body to normal insulin levels, necessitating higher insulin concentrations to maintain normal insulin function." (PMID 38052778, 2023). "Consistent with these previous findings, we observed that loss of adipose HK2 causes selective insulin resistance without affecting hepatic insulin signaling." (PMID 36920797, 2023). "Given that insulin resistance is shown to be strongly associated with NASH, AdipoRaMab may also be expected with its insulin-sensitizing effects to prevent NASH." (PMID 37948516, 2023). "In addition, recent studies have revealed the mechanism of the hypoglycemic effect of PPIs, such as improving insulin resistance and increasing insulin secretion." (PMID 37165049, 2023). "The insulin reduction is known to be independent from the BW modifications and may indicate that PG is consistent with the prevention of diseases bound to insulin resistance." (PMID 37630707, 2023). "In this review we provide an overview of the main SNPs in antioxidant genes involved in the promotion of insulin resistance with a focus on the potential role of microalgae-derived antioxidant molecules as novel nutritional tools to mitigate oxidative stress and improve insulin sensitivity." (PMID 36979141, 2023). "Also female gender, BMI, bilirubin, serum calcium, serum phosphorus PTH, fasting insulin, and insulin resistance were statistically significant predictors of OP among the NAFLD group." (PMID 36928441, 2023). "Both peptides could also enhance insulin signaling and mitigated insulin resistance in TNF-α-stressed preadipocytes." (PMID 37111032, 2023). "Aging is accompanied by deteriorations of insulin resistance (IR) and insulin secretion." (PMID 37443552, 2023). "Studies have shown that oxidative stress impairs insulin signaling and leads to insulin resistance." (PMID 37175603, 2023). "In addition, we successfully established optimal cut-off values for leptin in the assessment of obesity and insulin in the assessment of insulin resistance in patients with abnormal body mass index." (PMID 37373485, 2023). "The main manifestation of diabetes is hyperglycemia caused by a lack of insulin production or insulin resistance." (PMID 36677586, 2023). "In some in-vivo and clinical studies, the lack of vitamin D levels has been associated with increased insulin resistance and impaired insulin production." (PMID 37324274, 2023). "In the case of biochemical indices, participants from the control group had significantly higher HDL cholesterol parameters, but, at the same time, significantly lower insulin levels and lower insulin resistance indices than participants from the clinical group." (PMID 38139760, 2023). "Our findings suggest that impaired microvascular effects of insulin, i.e. microvascular insulin resistance, might be an important driver of HFpEF in older obese women with T2D." (PMID 37658327, 2023). "Emergent signaling events that counteract the canonical functions of insulin could contribute to the etiology of insulin resistance." (PMID 36808134, 2023). "All of these factors could be reasons for the varied interactions of IRS1 and IR, which lead to aberrant insulin transduction, followed by insulin resistance." (PMID 37664840, 2023). "Insulin resistance has been observed to promote Aβ generation in the brain, which can occur due to changes in insulin signal transduction, modulation of β-secretase and γ-secretase activities, and the accumulation of autophagosomes in an animal study using mice brains." (PMID 37511207, 2023). "SPISE is a potential surrogate marker for insulin resistance predicting emerging dysglycemia in children with overweight or obesity, and could, therefore, be applied in pediatric cohorts that lack direct insulin assessment." (PMID 36677025, 2023).
Insulin resistance (continued). "As adiponectin is known to play a role in insulin signaling and inflammatory pathways, its reduction may be partially responsible for the onset of insulin resistance and systemic inflammation and T2DM pathophysiology." (PMID 37152987, 2023). "However, the role of reduced β-cell mass and/or impaired insulin responses on feeding behavior and its relationship to body weight (BW) gain and insulin resistance have been difficult to disentangle." (PMID 37819196, 2023). "Furthermore, diabesity often manifests as a syndrome of insulin resistance, where the body’s cells are more resistant to insulin, resulting in elevated blood glucose amounts." (PMID 38201865, 2023). "We investigated whether enhancing CNS insulin levels or induction of CNS insulin resistance using an inhibitor of the insulin receptor altered the blood-to-brain transport of radioactively labeled insulin in young, healthy mice." (PMID 37076875, 2023). "Identification of signaling molecules that enhance islet compensatory responses in insulin-resistant states may blaze the trail for novel therapeutic approaches to prevent the progression of insulin resistance to T2D." (PMID 36574297, 2023). "Moreover, the level of plasma glycine correlates positively with insulin sensitivity but negatively with insulin resistance in view of the homeostasis model assessment for the beta cell function index." (PMID 37755297, 2023). "Notably, the impairment of insulin secretion due to iron-induced oxidative stress can lead to hyperglycemia and insulin resistance conditions, which are well-known features of T2DM." (PMID 38247487, 2023). "Only two weeks of high-fat diet (HFD) feeding induced an increase in adipose tissue (AT) and consequently led to hyperleptinemia and leptin resistance, proceeding to hyperglycemia and insulin resistance (IR) with impaired insulin signaling and glucose uptake mainly in the muscles and AT." (PMID 37686722, 2023). "In addition, apoA-IV−/− mice developed significant insulin resistance (indicated by HOMA-IR) with severe glucose intolerance even though their insulin levels were drastically higher than the WT mice." (PMID 38004234, 2023). "Indeed, inflammation-induced PIMT expression in skeletal muscle hampers insulin signaling leading to insulin resistance via the transcriptional downregulation of MEF2A and GLUT4 and attenuation of Akt phosphorylation." (PMID 36866247, 2023). "Furthermore, HSP72 contributes to sustaining increased insulin secretion in the presence of insulin resistance by making a direct protective contribution against β cell apoptosis." (PMID 37238736, 2023). "Furthermore, high level insulin acts as vasoconstrictor, thus insulin resistance related chronic hyperinsulinemia promotes vasoconstriction and results in hypertension which is the most attributed pathophysiology of vascular dementia." (PMID 36875407, 2023). "In addition, the chronic use of valproates is associated with an increase in the level of fast plasma insulin (FPI), the development of insulin resistance, especially in a subgroup of children and women." (PMID 37239168, 2023). "Elevated oxidative stress may be a major detrimental factor for insulin resistance, impaired mitochondrial function, abnormal energy metabolism, impaired insulin sensitivity, and dyslipidemia." (PMID 37764646, 2023). "Similar to the high insulin concentration that results from insulin resistance, IGF-1 levels may initially increase to compensate for IGF-1 resistance before gradually becoming depleted." (PMID 36670169, 2023). "The decrease in the levels of N-acetylglucosamine observed in NDM-insulin infants could reflect a major dysregulation of glucose availability that characterizes NDM-insulin infants in an early stage, preceding insulin resistance." (PMID 37762025, 2023).